KRT1 (keratin 1)
Description:
Structural component of intermediate filaments in suprabasal keratinocytes of stratified epithelia. Forms heteropolymers with a type I keratin, assembling into keratin intermediate filament networks that provide mechanical strength and structural stability to differentiating epidermal cells. May regulate the activity of kinases such as PKC and SRC by interacting with integrin beta-1 (ITB1) and the receptor of activated protein C kinase 1 (RACK1). In complex with C1QBP, acts as a high-affinity receptor for kininogen-1 (HMWK).
Synonyms: K1; KRT1A; AEI2; CK1; EHK; EHK1; EPPK; NEPPK
Tractability: Antibody: UniProt places it where antibodies can reach, with high confidence; its Gene Ontology location is reachable by antibodies, with high confidence. PROTAC: ubiquitination databases record sites on it; its protein half-life has been measured.
Gene: Protein-coding gene on chromosome 12 (52,674,736 to 52,680,407, reverse strand). Ensembl gene ENSG00000167768.
Subcellular location: Cell membrane; Cytoplasm
Pathways (Reactome):
Developmental Biology: Differentiation of Keratinocytes in Interfollicular Epidermis in Mammalian Skin; Formation of the cornified envelope; Keratinization
Immune System: FXIIa activates plasma kallikrein-kinin system; Neutrophil degranulation; Regulation of FXIIa and plasma kallikrein activity
Gene Ontology:
Molecular function: carbohydrate binding; protein binding; protein heterodimerization activity; structural constituent of skin epidermis; signaling receptor activity
Biological process: complement activation, lectin pathway; cornification; protein heterotetramerization; fibrinolysis; intermediate filament organization; keratinization; regulation of angiogenesis; response to oxidative stress
Cellular component: blood microparticle; cornified envelope; cytoplasm; extracellular exosome; extracellular region; keratin filament; membrane; nucleus; plasma membrane; cytoskeleton; cytosol; ficolin-1-rich granule lumen
Genetic constraint (gnomAD): Loss-of-function variants: 28 observed, 54.81 expected, observed/expected ratio (o/e) 0.51, 90% interval 0.38 to 0.7. The upper end of that interval is the gene's LOEUF score, 0.7, which puts it in group 2 of 6, group 1 being the genes least tolerant of losing a copy. Missense variants: 769 observed, 837.57 expected, observed/expected ratio (o/e) 0.92, 90% interval 0.87 to 0.97. Synonymous variants: 296 observed, 314.14 expected, observed/expected ratio (o/e) 0.94, 90% interval 0.86 to 1.04.
Homologues: Orthologues: chimpanzee KRT1 (98% identical), macaque KRT1 (96% identical), rabbit KRT1 (81% identical), guinea pig KRT1 (80% identical), pig KRT1 (77% identical), mouse Krt1 (76% identical), rat Krt1 (76% identical). Paralogues in human: KRT2 (64% identical), KRT3 (60% identical), KRT5 (59% identical), KRT76 (57% identical), KRT6B (56% identical), KRT6C (56% identical), KRT6A (56% identical), KRT77 (53% identical), KRT75 (52% identical), KRT4 (51% identical), KRT79 (49% identical), KRT73 (48% identical), and 56 more.
Diseases named in the same sentence as KRT1 in open-access papers:
KRT1 is named in the same sentence as 168 diseases in open-access papers, as found by Europe PMC text mining. Sharing a sentence is not in itself a finding about the gene and the disease. The quoted sentences say what the papers report.
epidermolytic ichthyosis (23 papers, 2009 to 2025). A rare keratinopathic ichthyosis (KPI), that is characterized by a blistering phenotype at birth which progressively becomes hyperkeratotic. "We presented a case of a 4-year-old boy with epidermolytic ichthyosis (EI) due to a KRT1 gene mutation." (PMID 40453098, 2025). "The genes KRT10 and KRT1 are expressed in keratinocytes during early differentiation, and their mutations cause epidermolytic hyperkeratosis." (PMID 37106791, 2023). "Three different missense variants affecting the homologous asparagine-188 of KRT1 in human patients have previously been described to cause epidermolytic hyperkeratosis." (PMID 36251712, 2022). "Other keratins that will play a role in the following are keratin 1 and 10, which are likewise associated with psoriasis and lichen planus, but also with epidermolytic ichthyosis." (PMID 36552866, 2022). "Missense variants affecting the homologous asparagine residue of the human KRT1 cause epidermolytic hyperkeratosis." (PMID 36251712, 2022). "For example, mutations in KRT5 or KRT14 are implicated in epidermolysis bullosa simplex, and KRT1 or KRT10 dysfunction causes bullous congenital ichthyosiform erythroderma; moreover, fragile skin structure is observed in almost all such conditions." (PMID 31581253, 2019). "Some authors suggest that the response to retinoids should also be influenced by the causal gene: patients with epidermolytic ichthyosis caused by a KRT10 mutation responding better than those with a KRT1 mutation." (PMID 29618363, 2018). "First, it is well-established that mosaic mutations can be passed on to offspring as germline heterozygous disease, for example, epidermal naevi with keratin 1 gene K1 and keratin 10 gene K10 mutations passed on as epidermolytic ichthyosis or mosaic NF1 being passed down as germline NF1." (PMID 36566878, 2023). "Genetic variants in KRT1 or KRT10 in humans typically present with an epidermolytic ichthyosis." (PMID 36251712, 2022). "Mutations in KRT1 or KRT10 are associated with EI, but also contribute to related disorders such as ichthyosis Curth‐Macklin, annular epidermolytic ichthyosis, ichthyosis with confetti, autosomal recessive and nevoid forms." (PMID 40741111, 2025). "For example, KRT1 and KRT10 have been associated with epidermolytic hyperkeratosis (EHK), an ichthyosis that is hallmarked by thick hyperkeratotic skin." (PMID 35900871, 2022). "Mutations in these genes lead to human genetic skin diseases such as epidermolytic hyperkeratosis (KRT1), ichthyosis vulgaris (FLG), seborrheic dermatitis (ZNF750), psoriasis (LCE3D), and harlequin ichthyosis (ABCA12)." (PMID 34543262, 2021). "Dominant negative mutations of the genes that encode keratin 1 and 10 (KRT1, KRT10) cause epidermolytic ichthyosis (EI), previously also known as epidermolytic hyperkeratosis and bullous congenital ichthyosiform erythroderma of Brocq." (PMID 33562614, 2021). "KRT1 and KRT10 are known to play a role in maintaining the integrity of the epidermis and are mutated in other blistering diseases such as epidermolytic ichthyosis." (PMID 24497829, 2014). "This gene is an ortholog of human keratin 1, which is known to be perturbed in humans with the ailment epidermolytic hyperkeratosis." (PMID 19701481, 2009). "The molecular analysis showed that the disease can be classified as a mosaic form of epidermolytic hyperkeratosis, since a mutation in the KRT1 gene was found in lesional skin, but not in DNA extracted from PBLs, thus indicating a postzygotic occurrence of the mutation." (PMID 34199056, 2021). "Epidermolytic hyperkeratosis or epidermolytic ichthyosis (EI, OMIM 113800) is an uncommon keratinization disorder which affects approximately 1:200000 infants and is caused by pathogenic heterozygous variants in the genes KRT1 and KRT10." (PMID 40741111, 2025).
epidermolytic ichthyosis (continued). "The KRT1-related epidermolytic hyperkeratosis presents with or without palmo-plantar keratoderma, while KRT10-related epidermolytic ichthyosis typically does not involve palmo-plantar keratoderma." (PMID 36251712, 2022).
psoriasis (18 papers, 2011 to 2025). An autoimmune condition characterized by red, well-delineated plaques with silvery scales that are usually on the extensor surfaces and scalp. "Their study revealed that the topical application of compound 3 (2 mM) significantly ameliorated hyperplasia and inflammatory cell infiltration and suppressed the expression of the psoriasis-associated genes S100a9, Krt1, Il17a, and Il22." (PMID 37111813, 2023). "HL and HP, but not CA and the positive control dithranol, increased the expression of the differentiation marker KRT1 that is reduced in psoriasis-like HPK." (PMID 33801280, 2021). "In contrast, we found that keratin 6 and keratin 1 are upregulated in psoriasis; both are involved in maintaining skin integrity and inflammation response, likely playing crucial mechanistic roles in plaque skin formation and the psoriatic process." (PMID 35154781, 2021). "It represents an early differentiation marker that is downregulated in psoriasis; therefore, we also investigated if the psoriasis cytokines can reduce KRT1 expression." (PMID 33801280, 2021). "In this regard, the role of Keratin 1 (KRT1) in atopic dermatitis and psoriasis was shown by comparative transcriptomics of the respective murine and human datasets." (PMID 31973112, 2020). "Treatment with TPA alters the normal differentiation program and suppresses keratin 1 expression, mimicking the incomplete cornification of psoriasis." (PMID 30544700, 2018). "In psoriasis, the early differentiation marker involucrin is highly expressed, while the other early differentiation factor, keratin 1, and the late differentiation marker, loricrin, are downregulated." (PMID 30544700, 2018). "On the other hand, some mouse phenotypes exhibit psoriasis-matching expression patterns for those DEGs/DEGPs that are most psoriasis-specific (e.g., K5-Tie2, Krt1-KO and imiquimod)." (PMID 26251673, 2015). "Conversely, other mouse phenotypes manifested increased expression of DEGPs most specific to psoriasis (e.g., K5-Tie2, Krt1-KO and imiquimod)." (PMID 26251673, 2015). "KRT1 is also a gene that was massively downregulated in psoriasis-like PHKs." (PMID 34641358, 2021). "The cytokeratin 1 knockout mice present inflammatory disease resembling psoriasis or atopic eczema." (PMID 25973436, 2015). "In comparison with normal samples, the glycolysis score was significantly higher in psoriasis samples in KRT5+ KRT14+ KC, KRT1+KRT10+ KC, and LDHA+SLC2A1+ KC (all P<0.001)." (PMID 37205116, 2023). "The effect of HL, HP and CA on gene expression of the hyperproliferation marker KRT17, the anti-microbial peptide DEFB4A, the early differentiation marker KRT1 and the glucose transporter GLUT1 were analyzed in psoriasis-like HPK." (PMID 33801280, 2021). "Proteins specific to the basement membrane region (KRT14, KRT5, KRT1) were decreased only slightly in psoriasis lesions with no significant overall trend (p = 0.346)." (PMID 26251673, 2015).
ichthyosis (14 papers, 2016 to 2025). Disorders of cornification that are characterized by visible scaling and/or hyperkeratosis of most or all of the skin. "The clinical and histological resemblance between EHK and inherited ichthyoses point to a possible role of functional mutations in genes encoding KRT1 and KRT10, which are essential for epidermal differentiation in the spinous layer." (PMID 39797176, 2024). "The finding of a de novo variant in an excellent functional candidate gene strongly suggests that KRT1:p.Asn190del caused the ichthyosis phenotype in the affected Chinese shar-pei." (PMID 36251712, 2022). "Mutations in the KRT1 gene were described in the case of a rare dominant ichthyosis type—Curth–Macklin form of ichthyosis hystrix (OMIM#146590)." (PMID 36076978, 2022). "Single gene selection to a normal phenotype may be found in patients exhibiting ichthyosis with mottling due to dominant KRT1 and KRT10 mutations, in which numerous clones of normal skin arise because of increased viability of cells that have converted to the homozygous wild type gene." (PMID 34284807, 2021). "Although not causing fragility, a translational frame shift and premature termination near the C-terminus of KRT1 results in a rare type of ichthyosis." (PMID 36374931, 2022). "In summary, to the best of our knowledge, this is the first case of a KRT1-related ichthyosis reported in domestic animals and the first case of ichthyosis in a Chinese shar-pei dog." (PMID 36251712, 2022). "This investigation documents a congenital cornification disorder in a Chinese shar-pei puppy due to a 3 base pair deletion in the KRT1 gene." (PMID 36251712, 2022). "Interestingly, a translational frame shift in KRT5 is responsible for a rare form of epidermolysis bullosa simplex, whereas a frame shift in KRT1 results in a rare type of ichthyosis." (PMID 39319188, 2024). "Since the phenotype of patchy erythema and ichthyosis was already described in the literature, as correlated to mutations in KRT1 and KRT10 genes, we sequenced these genes as well, but no mutations were found." (PMID 37762265, 2023). "Interestingly, we observed a significant increase in the transcripts for S100A8, S100A9, Krt1, and Saa1, which have been shown to maintain skin integrity, barrier function, inflammation, and ichthyosis in human skin." (PMID 27556734, 2016). "While cases of KRT1-related ichthyosis have been documented in humans, they have not been reported in dogs to date." (PMID 36251712, 2022). "CRIE, also known as ichthyosis with confetti, is a peculiar non-blistering KI subtype caused by dominant negative mutations in KRT10 or, less commonly, KRT1." (PMID 33081034, 2020).
breast carcinoma (13 papers, 2019 to 2024). "According to Funosas, KRT1 is overexpressed in squamous carcinomas and is linked to aggressive pathology in breast cancer." (PMID 37664033, 2023). "In the context of breast cancer, the KRT1 level is strongly reduced in breast cancer cells which assists them in achieving a metastatic phenotype." (PMID 35204811, 2022). "We previously engineered a breast cancer cell targeting peptide 18-4 that specifically binds cell surface receptor keratin 1 (K1) on breast cancer cells." (PMID 34063098, 2021). "Recently, it was found that KRT1 was highly expressed in breast cancer cells, and, thus, pointed as a new marker for breast cancer targeting." (PMID 33323544, 2020). "Keratin 1 (KRT1) is overexpressed in squamous carcinomas and associated with aggressive pathologies in breast cancer." (PMID 34123261, 2019). "KRT1 as a new marker for breast cancer targeting that is highly expressed on breast cancer cells.Upregulation of Keratin inhibits the invasion of MDA-MB-231 breast cancer cells.Keratin 1 has higher expression in nasopharyngeal carcinoma cell lines." (PMID 31749922, 2019). "In addition, keratin 1 (K1) is a novel receptor that is highly expressed on breast cancer cells and can also be used as a target for drug delivery." (PMID 37691919, 2023). "Other potential biomarkers for differentiating breast cancers and benign breast lesions include protein biomarkers such as the combination of epithelial membrane antigen and cytokeratin-1 (EMA and CK1; AUC of 0.9010), and developmental endothelial locus-1 (Del-1; AUC of 0.9200)." (PMID 31769433, 2019). "Herein we report the first red-emitting Trp-based fluorogenic amino acid and its optimal incorporation into a cyclic peptide to image the protein keratin 1 (KRT1), which is overexpressed in aggressive breast cancer tumours." (PMID 34123261, 2019).
Palmoplantar keratoderma (8 papers, 2018 to 2025). Abnormal thickening of the skin of the palms of the hands and the soles of the feet. "In one family, the possible cause of palmoplantar keratoderma was detected—a variant in the KRT1 gene (NM_006121.4): c.931G>A (p.(Glu311Lys))." (PMID 36076978, 2022). "This aligns with prior research in humans and model organisms, where KRT1 gene mutations disrupt keratin filament assembly, leading to hyperkeratotic disorders like palmoplantar keratoderma, characterized by abnormal epidermal thickening analogous to the keratinization process in horn development." (PMID 41473116, 2025). "For instance, for hystrix ichthyoses, it has been postulated that mutations in KRT1 result in a phenotype with the presence of palmoplantar keratoderma, the IH-CM type, while mutations in KRT10 cause the Lambert type (IH-L), in which palmoplantar keratoderma is absent." (PMID 29689068, 2018). "Various skin abnormalities, such as hyperkeratosis, abnormality of the plantar skin of the foot, palmoplantar keratoderma, subcutaneous nodules and erythema, were associated with GJA1, KRT1, KRT2, PSEN1 and INSR." (PMID 37185447, 2023). "Interestingly, KRT1-associated EHK has an accompanying palmoplantar keratoderma that is generally absent in KRT10-associated EHK." (PMID 35900871, 2022). "Thus, deficiencies in KRT10 likely do not manifest as palmoplantar keratoderma because, at acral sites, KRT9 is the main binding partner of KRT1." (PMID 35900871, 2022).
Hyperkeratosis (7 papers, 2016 to 2025). Hyperkeratosis is a histopathological term defining a thickened stratum corneum and may be present in many different skin conditions, with many possible overlaps. "Similar to other described cases, PPK of varying severity is associated with most cases of IWC type I (KRT10), whereas disproportionately severe hyperkeratosis has been reported in IWC type II (due to KRT1)." (PMID 35172852, 2022). "Altered KRT1/KRT10 dimer formation due to variants affecting the structure of the paired 2B and V2 domains leads to severe acanthosis and hyperkeratosis in humans, reflecting the histologic features observed in the affected Chinese shar-pei." (PMID 36251712, 2022). "Given the hyperkeratosis observed in VDR-KO rats through HE staining, we conducted Western blotting using the antibody against the keratin marker Krt14 and anti-pan-keratin antibody (PCK26), which detects rat keratin 1 (66 kDa), keratin 5 (58 kDa), and keratin 8 (52 kDa)." (PMID 39796272, 2025).
melanoma (7 papers, 2020 to 2025). A malignant, usually aggressive tumor composed of atypical, neoplastic melanocytes. "Survival analysis revealed that the high transcription levels of KRT1/5/6/14/15/16/17 were associated with low overall survival in melanoma patients." (PMID 33441834, 2021). "A high KRT1 expression was significantly associated with poor OS in melanoma patients." (PMID 33441834, 2021). "Elevated levels of KRT1/5/6/14/15/16/17 have been found to correlate with lower overall survival in melanoma patients, confirming that the epidermis/keratinocyte signature can also provide information on outcome." (PMID 41465101, 2025). "A recent study found that a higher expression of KRT1 and KRT17 is associated with low overall survival in melanoma." (PMID 38791062, 2024). "In conclusion, our study is the first to demonstrate that KRT1/2/5/6/8/10/14/15/16/17 expression is elevated in primary melanoma compared with metastatic, and that high KRT1/5/6/14/15/16/17 mRNA levels predict poor prognosis." (PMID 33441834, 2021). "We found that the mRNA levels of KRT1/2/5/6/8/10/14/15/16/17 were significantly differential expressed between primary melanoma and metastatic melanoma." (PMID 33441834, 2021). "In our study, GEO and TCGA datasets revealed that the expression of KRT1 was higher in primary melanoma than in metastatic melanoma." (PMID 33441834, 2021). "A smaller tissue from patient ID 9561, collected in 2008, had four clusters, including melanoma (PMEL, TYRP1), immune cells (TMSB4X, IL32), keratinocytes (KRT10, KRT1, DSG1), and fibroblast areas (COL1A2, COL1A1, DCN)." (PMID 39846232, 2025).